FANCM (FA complementation group M)
Diseases named in the same sentence as FANCM in open-access papers (continued):
Sharing a sentence is not in itself a finding about the gene and the disease.
breast cancer (continued). "The burden analyses including all the rare 673 FANCM MVs did not indicate any statistically significant association with breast cancer risk either in the analysis of combined population- and family-based studies or when these groups were analysed separately." (PMID 36707629, 2023). "Notably, one family in the present study, with an accumulation of PDAC and breast cancer, revealed a pathogenic SUFU variant co-segregating with PDAC and a FANCM variant segregating with breast cancer." (PMID 34357098, 2021). "We described the geographic distribution and relative prevalence of 27 different FANCM PTVs detected in 114 female European breast cancer probands with no pathogenic variants in BRCA1 or BRCA2 genes." (PMID 31991861, 2020). "Although the FANCM p.Q1701* mutation is well established as genetic risk factor for breast cancer development, there are no studies addressing the FANCM somatic events in patient tumors." (PMID 32680567, 2020). "FANCM:c.1491dup was observed in two women with breast cancer." (PMID 29351780, 2018). "Screening of the other two FANCM variants exposed only one additional c.4025_4026delCT carrier and no c.5293dupA carriers among 862 familial breast cancer patients, and these were not studied further." (PMID 28702895, 2017). "The mutations in FANCM were identified in the control series and thus were not considered to contribute to elevated breast cancer risk." (PMID 22347400, 2012). "FANCM c.5101C > T and c.5791C > T did not associate with overall breast cancer risk." (PMID 40009290, 2025). "The lack of associations of FANCM MVs with breast cancer risk in the analyses of only population-based studies could be explained by the presence of other unmeasured risk variants aggregating in families that may interact with FANCM MVs." (PMID 36707629, 2023). "Notably, FANCM (OMIM 609644) variants have been reported to confer risk for CRC and breast cancer." (PMID 33118316, 2020). "For example, miR-449a has been reported to target EME1 and downregulate BRCA2 and RAD51 in breast cancer, while miR-146 targets and/or downregulates FANCM and BRCA1 in cervical, gastric, and breast cancer cells." (PMID 41008855, 2025). "We determined that 106 of these genes, including breast cancer type 1 (BRCA1), SUZ12 polycomb repressive complex 2 subunit (SUZ12), and FA complementation group M (FANCM), were involved in the cell cycle process." (PMID 38514462, 2024). "In this study, we report FANCM PTV carrier frequencies among 44,803 breast cancer cases from 19 countries." (PMID 37444426, 2023). "More recently, we tested FANCM:p.Gln1701*, p.Gly1906Alafs12*, and c.1972C >T (p.Arg658*), which is the third most common FANCM PTV found in Europeans, in a large study including breast cancer cases and controls from 19 European countries." (PMID 34584094, 2021). "FANCM:c.5101 C >T (p.Gln1701*) is another PTV identified in a Finnish population study, by exome sequencing of 11 breast cancer families." (PMID 34584094, 2021). "In addition, we provide evidence that lack of FANCM protein and truncating variants identified in breast cancer patients are associated with increased sensitivity to the PARPi olaparib suggesting a therapeutic opportunity to treat FANCM-associated breast tumors that warrants further investigation." (PMID 31700994, 2019). "We report here a Finnish breast cancer patient homozygous for FANCM c.5101C>T p.(Gln1701*) diagnosed with triple‐negative breast cancer at the age of 35 years." (PMID 40832744, 2025).
breast cancer (continued). "A sequencing analysis of the entire FANCM coding region showed an excess of a third common PTV, the c.1972C > T (p.Arg658*, rs368728266), in German breast cancer cases versus controls, and confirmed that FANCM PTVs have a particularly high risk (OR = 3.75) for TNBC." (PMID 31991861, 2020). "In this study, we did not detect the RAD51C, RAD51D, FANCM, or PALB2 mutations among male breast cancer patients." (PMID 28874143, 2017). "Given the relatively low frequency of RAD51C, RAD51D, FANCM, and PALB2 mutations among unselected female breast cancer patients, the absence of the studied mutations in the MBC series was not unexpected." (PMID 28874143, 2017). "Our finding that the breast cancer cell lines expressing a high level of miR146a failed to express the FANCM protein is particularly intriguing." (PMID 27351285, 2016). "However, a recent publication described that biallelic FANCM mutations do not cause classical FA and therefore should not be considered a canonical FA gene, although these biallelic carriers showed risk for breast cancer, chemotherapy toxicity and may display chromosome fragility." (PMID 32235514, 2020).
ovarian carcinoma (16 papers, 2016 to 2025). A malignant neoplasm originating from the surface ovarian epithelium. "Loss‐of‐function mutations within the FANCM Gene increase the susceptibility of breast and ovarian cancer." (PMID 34331411, 2021). "Here we report the application of massively parallel sequencing to characterise the germline mutation spectrum of RECQL and FANCM in unselected women from South-West Poland and West Ukraine affected with breast or ovarian cancer." (PMID 29351780, 2018). "The present study of breast and ovarian cancer cases from Poland and Ukraine identified 1/427 (0.23%) carrier of the truncating FANCM:c.1972C > T mutation." (PMID 29351780, 2018). "We estimated the relative risk of ovarian cancer associated with deleterious mutations in the FANCM gene as the odds ratio (OR), using data from the case-control studies that were not family based." (PMID 28881617, 2017). "In this current case–control study, we evaluated the breast and ovarian cancer risk for the FANCM c.5791C>T mutation as well as for c.4025_4026delCT and c.5293dupA variants among Finnish population." (PMID 28702895, 2017). "The finding of a pathogenic variant in FANCM during this specific analysis is promising as it affirms our candidate gene rationale and to our knowledge, marks the first known case of a FANCM deleterious variant in an ovarian cancer patient." (PMID 28591191, 2017). "The top 10 genes with most deleterious mutations in the Chinese ovarian cancer population were MC1R (12%), MLH1 (9%), PRKDC (8%), KIF1B (8%), FANCM (7%), FANCI (6%), PRSS1 (6%), SDHA (6%), BRCA2 (6%), and CFTR (5%)." (PMID 38817903, 2024). "Monoallelic pathogenic variants in FANCD1/BRCA2, FANCS/BRCA1, FANCJ/BRIP1, FANCM, FANCN/PALB2, and FANCO/RAD51C have been linked to familial breast and ovarian cancer." (PMID 36428697, 2022). "In this study, we have characterised the spectrum of FANCM and RECQL mutations in women affected with breast or ovarian cancer from South-West Poland and West Ukraine." (PMID 29351780, 2018). "In this study, we have genotyped 68 MBC patients for the known breast or ovarian cancer associated mutations in the Finnish population in CHEK2, PALB2, RAD51C, RAD51D, and FANCM genes." (PMID 28874143, 2017). "The patient's family history is unremarkable, with no reported cases of breast or ovarian cancer, a fact that can be attributed to the significant lower penetrance of FANCM mutations." (PMID 31223512, 2019). "FANCM mutation testing in women with HGSOC might also have clinical utility through targeted treatment with Poly (ADP-ribose) polymerase (PARP) inhibitors, which are currently being evaluated in women with BRCA1 and BRCA2 associated ovarian cancer." (PMID 28881617, 2017). "In the scope of the German Consortium for Hereditary Breast and Ovarian Cancer, other candidate genes (e.g., NBN, FANCM, XRCC2, and RECQL) are currently co-analyzed for research purposes and their significance in contributing to breast and ovarian cancer is under investigation." (PMID 34680878, 2021).
anemia (15 papers, 2013 to 2025). A reduction in the number of red blood cells, the amount of hemoglobin, and/or the volume of packed red blood cells. "A truncating mutation in the Fanconi anemia complementation group M (FANCM) gene was detected in heterozygosity, namely, p.Arg658Ter (c.1972C>T, rs368728266)." (PMID 31223512, 2019). "FANCM, together with other Fanconi anemia (FA) proteins, detects interstrand crosslink (ICL) damage and associates with chromatin, serving as a docking site for the core FA complex." (PMID 39911859, 2025). "Here, using CRISPR-Cas9 strategies, we validate FANCM (Fanconi anemia complementation group M) as a crucial target for ALT-associated cancers and demonstrate its importance in both in vitro and in vivo models." (PMID 40125273, 2025). "Hef is an archaeal member of the DNA repair endonuclease XPF (XPF)/Crossover junction endonuclease MUS81 (MUS81)/Fanconi anemia, complementation group M (FANCM) protein family that in eukaryotes participates in the restart of stalled DNA replication forks." (PMID 24049073, 2013). "To understand how ICL is specifically recognized by the Fanconi anemia proteins FANCM and FAAP24, we determined the structure of the HhH domain of FAAP24." (PMID 23661679, 2013). "Among these genes, Fanconi anemia Complementation Group M (FANCM) and Mediator of DNA damage checkpoint protein 1 (MDC1) may be related to CSR due to their known roles facilitating a DNA damage response leading to DNA repair." (PMID 34628594, 2022). "FANCM is the most highly conserved member of the Fanconi Anemia complementation group (FANCG)." (PMID 28591191, 2017). "The FANCM gene is one of the elements of the Fanconi Anemia (FANC) pathway responsible for DNA crosslinks repair, possibly through coordination of three main DNA repair systems: nonhomologus endjoing (NHEJ), homologus recombination (HR) and translesion DNA synthesis (TLS)." (PMID 28376765, 2017). "We also found that several Fanconi anemia (FA) proteins (e.g., FANCA, FANCF, FANCM, FANCD2), which are central proteins of inter-strand crosslink (ICL) repair, favored MMEJ." (PMID 38909016, 2024). "Additionally, we found a clique that consists of Fanconi anemia (FA) proteins (FANCF, FANCM, FANCG and FANCD2) and a third clique with two FA proteins together with BLM and RMI2." (PMID 38909016, 2024).
triple-negative breast carcinoma (8 papers, 2017 to 2025). An invasive breast carcinoma which is negative for expression of estrogen receptor (ER), progesterone receptor (PR), and human epidermal growth factor receptor 2 (HER2). "We identified presumed compound heterozygous FANCM variants in a woman with triple-negative breast cancer." (PMID 38996041, 2025). "FANCM protein truncating variants (PTVs) are emerging as risk factors for ER-negative and triple negative breast cancer." (PMID 34584094, 2021). "Further support for our findings comes from a Finnish study that reported a significant association for FANCM Q1701X with triple negative breast cancer." (PMID 28881617, 2017). "The current results provide further support for the previously suggested association between FANCM mutations and triple-negative breast cancer." (PMID 28702895, 2017). "Evidence from literature, including the BRIDGES study, indicates that germline protein truncating variants (PTVs) in FANCM confer moderately increased risk of ER-negative and triple-negative breast cancer (TNBC), especially for women with a family history of the disease." (PMID 36707629, 2023).
Infertility (7 papers, 2018 to 2025). "The link between infertility and risk of cancer was recently underlined, with mutations found in genes like FANCM." (PMID 38441556, 2024). "Our objective is to validate that FANCM p.P648Lfs*16 is the PV causing infertility in this family." (PMID 29895858, 2019). "Several genes critical in repairing DNA double-strand breaks (DSB) have been linked to hereditary cancer syndromes and infertility in both men and women (e.g. BRCA2, FANCM, XRCC2)." (PMID 40060932, 2025). "Some hereditary cancer genes (e.g. BRCA2, FANCM, MLH1, WT1) have been directly linked to human infertility." (PMID 40060932, 2025). "Studies have shown that patients with biallelic pathogenic variants of FANCA, FANCM, FANCD1, FANCU, and patients with monoallelic pathogenic variants of FANCA, FANCD1, FANCL exhibited gonadal dysfunction and infertility." (PMID 37563658, 2023). "In FA patients, problems associated with gonadogenesis such as hypogonadism, and infertility are common, particularly male infertility, and a recent study identified biallelic loss-of-function FANCM mutations as cause of non-obstructive azoospermia." (PMID 30540754, 2018). "A patient-derived mutation truncating the C-terminal HhH domain (p.Arg1931∗; rs144567652) associated with cancer predisposition and infertility showed similar defects, and is consistent with previous observations that both the C-terminal region and FAAP24 are essential for FANCM function." (PMID 40447800, 2025). "Western blot analysis using an antibody recognizing an epitope between FANCM amino acids 600 and 700 confirmed the absence of full-length FANCM protein from the blood samples of all three infertile brothers." (PMID 29895858, 2019).
Azoospermia (5 papers, 2018 to 2023). Absence of any measurable level of sperm,whereby spermatozoa cannot be observed even after centrifugation of the semen pellet. "It was reported that variants in FANCM (MIM: 609644) might cause azoospermia or oligospermia." (PMID 34976027, 2021). "In otherwise healthy males, who have non-obstructive azoospermia, biallelic mutations in FANCM cause a Sertoli-cell only syndrome, where the tubules are depleted of spermatogonia and spermatocytes." (PMID 33500205, 2021). "While FA patients usually experience fertility defects, mutations of many FA genes, including FANCM, FANCU, and FANCA, also lead to POI in females and non-obstructive azoospermia (NOA) in males." (PMID 37580696, 2023). "Furthermore, pathogenic variants in other DNA repairs genes such as FANCM, FANCA and XRCC2 also cause meiotic arrest and non-obstructive azoospermia." (PMID 33500205, 2021). "Similarly, different bi-allelic mutations in FANCM were suspected in independent studies as being the causes for early menopause, non-syndromic POI, and non-obstructive azoospermia." (PMID 31535215, 2019).
Bloom syndrome (5 papers, 2008 to 2025). Bloom syndrome (BSyn) is a rare chromosomal breakage syndrome characterized by a marked genetic instability associated with pre- and postnatal growth retardation, facial sun-sensitive telangiectatic erythema, increased susceptibility to infections, and predisposition to cancer. "BLM, which is mutated in Bloom Syndrome, is a helicase proposed to resolve DNA secondary structures of AT-rich CFSs but differently from FANCM and works together with FANCM to preserve the integrity of CFSs." (PMID 40860596, 2025). "FANCM was reported to interact with the Bloom syndrome (BS) complex using its highly conserved protein-protein interaction motifs, MM1 and MM2." (PMID 26596371, 2015). "Interestingly, the recruitment of FANCM requires its direct interaction with Bloom syndrome complex composed of BLM helicase, Topoisomerase 3α, RMI1 and RMI2; as well as the helicase activity of BLM." (PMID 28058110, 2016). "We also suspect that a similar pathway is promoted by FANCM in humans, and in this regard it is interesting to note that the FA core complex copurifies with the Bloom syndrome complex, which contains the orthologs of Rqh1 (=BLM), Top3 (=Top3α), and Rmi1 (=BLAP75)." (PMID 18851838, 2008).
male infertility (5 papers, 2018 to 2025). The inability of the male to effect fertilization of an ovum after a specified period of unprotected intercourse. "However, there is still a lack of evidence to explain the association between different FANCM variants and male infertility phenotypes." (PMID 34976027, 2021). "Therefore, our findings that a homozygous loss-of-function FANCM PV impaired spermatogenesis and caused male infertility provide novel insights into genotype–phenotype correlations for biallelic FANCM PV." (PMID 29895858, 2019). "Because the patients declined to provide testicular tissues, and to understand whether the FANCM p.P648Lfs*16 PV is indeed the cause of male infertility, we generated a mouse model with a homozygous Fancm p.R638Rfs*8 PV (FancmΔC/ΔC) nearly equivalent to that in our patients." (PMID 29895858, 2019). "A 2018 review identified 78 genes related to male infertility, but only two were convincingly linked to the SCOS phenotype, both of which are autosomal recessive, namely FANCA and FANCM." (PMID 41488147, 2025). "Recently, another study identified a homozygous FANCM PV in three brothers with idiopathic male infertility." (PMID 34976027, 2021). "A homozygous PV in FANCM (c.1946_1958del, p.P648Lfs*16) was found cosegregating with male infertility." (PMID 29895858, 2019). "Altogether, these findings revealed that male infertility is a novel phenotype of the biallelic FANCM PV in humans." (PMID 29895858, 2019). "Hence, although the observation of cellular ICL sensitivity and male infertility in patients might be suggestive of FA, it appears that the homozygous FANCM PV do not cause FA." (PMID 29895858, 2019).
astrocytoma (4 papers, 2021 to 2024). "Immunohistochemical analyses in the testicular and tumor tissues of the patient and adequate controls showed, for the first time, not only the existence of a cytoplasmic and not nuclear pattern of FANCM in astrocytoma but also in non-mitotic neurons." (PMID 38927643, 2024).
colorectal cancer (4 papers, 2019 to 2025). A primary or metastatic malignant neoplasm that affects the colon or rectum. "It validates a FANCM risk variant previously reported as associated with colorectal cancer, but not confirmed." (PMID 33118316, 2020). "Moreover, Tel+ human colorectal carcinoma cells, mouse embryonic fibroblasts and chicken lymphoblasts knocked-out for FANCM were successfully generated and proliferated normally unless challenged with DNA damage." (PMID 31138795, 2019).
hereditary cancer (4 papers, 2017 to 2025). Malignant neoplasms occurring in families at a rate greater than that expected by chance and caused by germline mutations in a specific gene. "A prospective cohort of 1021 unrelated cancer cases with clinical suspicion of hereditary cancer was screened for mutations in the following 14 FA genes: FANCA, FANCB, FANCC, FANCD2, FANCE, FANCF, FANCG/XRCC9, FANCI, FANCL/PHF9, FANCM, FANCP/SLX4, FANCQ/ERCC4, FANCR/RAD51 and FANCU/XRCC2." (PMID 32235514, 2020).
osteosarcoma (4 papers, 2016 to 2024). A usually aggressive malignant bone-forming mesenchymal neoplasm, predominantly affecting adolescents and young adults. "In osteosarcoma, SMARCAL1, IRS1, SUB1, HMGA2, and FANCM were identified as Supertargets." (PMID 37297004, 2023). "To validate this approach, we performed TAILS in the ALT-positive osteosarcoma cell line U2OS using 3 pooled sgRNA oligos against non-targeting sequences (sgCtrl), the Bloom DNA helicase (sgBLM), and the DNA helicase FANCM (sgFANCM)." (PMID 39605432, 2024).
bone marrow failure (3 papers, 2019 to 2024). "Because patients with biallelic FANCM PV were recently reported with early-onset cancers but without bone marrow failure, the typical malignancy of FA, we thus investigated whether our FANCM PV could cause bone marrow failure in our patients and mice." (PMID 29895858, 2019).